KLF4 (KLF transcription factor 4)
Diseases named in the same sentence as KLF4 in open-access papers (continued):
Sharing a sentence is not in itself a finding about the gene and the disease.
infection (continued). "Also, the timing within the course of an infection may influence whether KLF4 acts in a pro- or anti-inflammatory manner in macrophages." (PMID 40313940, 2025). "In one such example, KLF4 has been implicated in the epigenetic reprogramming of monocytes in bacillus Calmette-Guérin (BCG) vaccination, which enhances cellular responsiveness to subsequent infections, as demonstrated in a controlled randomized clinical trial using attenuated yellow fever virus." (PMID 40552304, 2025). "Furthermore, we studied the function of KLF4 in murine PMNs after infection with S. pneumoniae." (PMID 33613460, 2020). "Infection with S. Typhimurium generally stimulates LPS-dependent M1 macrophage profile in murine macrophages while PGE2 is associated with M2 polarization profiles, for example, via cyclic-AMP responsive element binding (CREB) induction of Krupple-like factor 4 (KLF4)." (PMID 30429830, 2018). "Since increase in KLF4 expression during infection could not be linked to transcriptional regulation, we investigated a possible miRNA-dependent mechanism of translational upregulation of KLF4." (PMID 28558034, 2017). "Making use of data of the Mtb-infected macrophage transcriptome (at 4 h and 24 h post-infection) available from our laboratory, we narrowed down on a set of transcription factors that are reportedly important players in M1/M2 macrophage polarization, namely KLF4, C/EBPβ and CREB." (PMID 28558034, 2017). "The co-transfection of gCblue, GR, and KLF4 stimulated productive infection approximately 3-fold when DEX was added to cultures, which was significantly different than the effect observed with KLF4 alone." (PMID 40006984, 2025). "A previous study demonstrated KLF4 cooperates with GR and DEX to stimulate BoHV-1 productive infection." (PMID 40006984, 2025). "The results show that KLF4 mRNA expression was significantly upregulated in PEDV-infected cells and peaked at 48 h post-infection." (PMID 40867674, 2025). "Some upstream regulators were common between both parasite stages (MYC, KLF4, and SMAD3) albeit with variations in the number and/or identity of downstream targets in each type of infection." (PMID 35430587, 2022). "Myeloid KLF4 KO mice showed reduced levels of TNF-α, KC and IL-1β and increased levels of IL-10 in BALF and plasma after infection with S. pneumoniae." (PMID 34589087, 2021). "We overexpressed KLF4 in MDA-MB-231 and MDA-MB-468 cells by infection with AdGFP or AdKLF4 and quantified the number of live cells 3, 4, and 5 days thereafter." (PMID 32552913, 2020). "While R6× induced KLF4 already after 3 h of infection with an MOI of 1, higher MOIs (10 and 100) and longer infection times (6 h) were needed with D39 and D39Δcps." (PMID 33613460, 2020). "To evaluate the induction of tumorigenicity in HaCaT cells by OSKM-N factors, we obtained cells that stably expressed OCT4, SOX2, KLF4, C-MYC, or NANOG by infection with lentiviral particles after the selection period." (PMID 31885625, 2019). "The level of the epigenetic marker at the position of genes WNT10A, JUNB, FOSL2, TNFAIP3, KLF4 and EDN1 was increased, and decreased at the position of genes MYCN and PCSK9, as was demonstrated by using the in vitro HCV-infection systems." (PMID 31216276, 2019). "Fibroblasts from the CLN5 patient were reprogrammed by the expression of SOX2, OCT3/4, KLF4 and MYC after infection with a Sendai virus delivery vector, in order to produce integration-free CLN5Y392X iPSCs." (PMID 28468312, 2017). "Following infection, we observed that each of these shRNAs individually blocked HPV amplification indicating that the effects are specific for KLF4." (PMID 27386862, 2016). "Very little is known regarding KLF4 protein expression in B cells, in which EBV normally enters the latent form of infection." (PMID 26431332, 2015). "The cells were then used for generating iPS cells after infection with retroviruses containing human OCT3/4, SOX2, C-MYC and KLF4." (PMID 24577094, 2014).
infection (continued). "Many LCM-associated regulons were not altered by infection (C/EBPβ), while others were lost (RARG and MAF) and others gained (KLF4, STAT3, FOSB, and BHLHE40)." (PMID 36948193, 2023). "In contrast to KLF15, KLF4 protein levels were not increased following infection of Vero or SH-SY5Y." (PMID 34203849, 2021). "Next, myeloid KLF4 KO and KLF4 WT mice were transnasally infected with a higher dosage of NCTC 7978 pneumococci (5x105 CFU) and clinical symptoms of infection (breathing quality, reaction to external stimuli, raised fur) were monitored every 12 hours for 48 hours." (PMID 34589087, 2021). "Under conditions of infection with WT V. vulnificus, HT-29 cells upregulated KLF2, KLF4, and KLF6 and downregulated NLRP3, TLR4, and CXCR4, suggesting that the MARTX toxin interrupts inflammatory responses, NF-κB signaling, and mitogen-activated protein kinase (MAPK) signaling in infected cells." (PMID 32817457, 2020). "Cells infected with KLF4 + ΔNp63α lentivirus had increased expression of basal keratinocyte genes (e.g. KRT14, ITGA3) and reduced expression of fibroblast genes (e.g. MME, VIM) compared to control infections." (PMID 31216312, 2019). "On the contrary, neither Pparγ1 nor Pparγ2 was expressed in the SOX10+ cells generated by Sox10/c-Myc/Klf4 infection, showing that the SOX10+ cell population did not contain pre- or pro-adipocytes." (PMID 26873953, 2016). "In this system, primary iPS cells were generated first by infection of neonatal tail-tip fibroblasts, carrying the ROSA-rtTA transactivator, with lentiviruses expressing Oct4, Sox2, Klf4 and cMyc, each under the control of a doxycycline (dox)-inducible promoter." (PMID 22028872, 2011). "In addition, mice lacking Klf4-dependent cDC2s show reduced survival by week 7 of S. mansoni infection, comparable to infection of IL-4−/− mice, implying an inability to induce a type-2 immune response." (PMID 37012228, 2023). "The uneventful later course (reincrease of body temperature, stable body weight, stable survival rate until day 10) might indicate that adaptive immunity, which transpires several days post-infection, is not impaired in myeloid KLF4 knockout mice." (PMID 34589087, 2021). "After 5 days of Klf4 expression ± recombinant protein treatment (designated day 0), treatment groups and untreated MEFs were (i) collected and analysed by FACS for proportion of Thy1+ cells and (ii) replated for a second infection of retrovirus for mOct4 and mSox2." (PMID 22619682, 2012). "Because lentiviral infection seriously influenced CAL27 cells growth both in the control and KLF4-shRNA-transduction group, there is no significant growth difference between the two groups by MTT assay." (PMID 26517087, 2015). "Under conditions of Klf4 knockdown, bacterial counts were higher in infected cells when the cells were treated with L-NAME after infection, compared to cells that were not treated with L-NAME, suggesting that KLF4 regulates bacterial survival at least in part through regulating iNOS and NO levels." (PMID 28558034, 2017). "First, pig iPSCs could be induced by KLF4, SOX2, and MYC (but not OCT4) infection, although transgenes were not silenced." (PMID 27336671, 2016).
inflammation (9 papers, 2016 to 2026). Aberrant reaction of the microcirculation characterized by movement of fluid and leukocytes from the blood into extravascular tissues. "In vascular inflammation, estrogen induces the transdifferentiation of vascular smooth muscle cells into macrophage-like cells via KLF4, underscoring its role in cellular plasticity." (PMID 40640934, 2025). "Both KLF2 and KLF4 have previously been reported in vascular inflammation and as targets of miR-92a." (PMID 36768805, 2023).
cardiovascular diseases (8 papers, 2013 to 2025). "Studies have reported that KLF4 and KLF5 are correlated with several cardiovascular diseases, but population-based studies on associations between HT and KLF4 or KLF5 have rarely been reported." (PMID 39187911, 2024). "The transcription factors KLF4, retinoic acid receptor, TCF21, AHR, and erythroblast transformation-specific related gene are all to some extent involved in vSMC phenotype switching in cardiovascular diseases, with a key role for KLF4." (PMID 34470477, 2021). "In addition, a pivotal contribution of KLF4-dependent regulation of macrophage function to cardiovascular disease is exemplified by the observation that myeloid Klf4 deficiency augments vascular inflammation and atherosclerotic lesion formation in Apoe−/− mice." (PMID 29942807, 2018). "Krüppel-like factor 4 (KLF4) is the most well-recognized driver of synthetic VSMC and has been shown to contribute to the development of cardiovascular diseases, including AAA." (PMID 38881898, 2024). "Despite its wide distribution, critical functions and sensitivity to various cardiovascular diseases, the role of Klf4 in activation of cardiac fibroblasts has not been fully defined." (PMID 23646205, 2013).
prostate (8 papers, 2015 to 2023). "In terms of prostate carcinogenesis, inhibition of the KLF4/P13/Akt/p21 pathway by microRNA-7 repressed the stem cell attributes of PCa cells and their tumorigenic potential." (PMID 29017567, 2017). "Taken together, our findings identify a regulatory mechanism by which AR upregulates KLF4 expression directly and transcriptionally; subsequently, KLF4 increases miR-1 expression levels and sustains suppressed prostate tumorigenesis." (PMID 27991915, 2016). "In the present study we identified miR-7 as a novel miRNA to specifically suppress the PCSCs' stemness and prostate tumorigenesis by directly inhibiting a key stemness factor KLF4." (PMID 26172296, 2015). "Together, these findings demonstrated that restoration of miR-7 impaired the PCSCs' stemness and prostate tumorigenesis by suppressing KLF4/PI3K/Akt/p21 signaling." (PMID 26172296, 2015). "Furthermore, we also demonstrated that miR-7 restoration inhibits overall prostate tumorigenesis through KLF4/PI3K/Akt/p21 pathway." (PMID 26172296, 2015). "Previous report has shown that miR-7 abrogates KLF4/PI3K/Akt pathway and inhibits prostate tumorigenesis." (PMID 28239300, 2017). "Given that restoration of miR-7 abrogates KLF4/PI3K/Akt pathway and eventually inhibits prostate tumorigenesis, we attempted to identify additional downstream cascade effectors of the signaling pathway." (PMID 26172296, 2015).
adenocarcinoma (6 papers, 2012 to 2022). A common cancer characterized by the presence of malignant glandular cells. "Another study showed a significant decrease in KLF4 expression in adenocarcinomas compared with that in normal tissue, while significant KLF4 overexpression was detected in SCLCs." (PMID 35982899, 2022). "In our TNBC model, we found up-regulation of Pou5F1 (Oct-3/4), Kit, Cd24 and Itga6 (Cd49f) in epithelial-like adenocarcinoma areas of primary tumors, while Klf4, Sox2, Cripto-1 were expressed in the mesenchymal/EMT-like regions." (PMID 26059540, 2015). "Within the cohort of adenocarcinoma patients, there was a significant change in expression of the Yamanaka factors, OCT-4 (p<0.001), KLF4 (p<0.05) and C-MYC (p<0.001)." (PMID 29069808, 2017).
gastrointestinal tumors (6 papers, 2017 to 2025). "Based on the evidence presented in our meta-analysis, loss of KLF4 expression could be a poorer prognostic biomarker in most kinds of digestive system tumors except ESCC." (PMID 29062163, 2017). "KLF4 was lowly expressed in gastrointestinal tumors, and the low expression in COAD and READ was statistically significant (P < 0.05)." (PMID 34367275, 2021). "Consistent with the previous reports, the results of GEPIA bioinformatics analysis exhibited that KLF4 showed low expression in gastrointestinal tumors." (PMID 34367275, 2021). "Increasing evidence suggested the abnormal expression of KLF4 was detected in many digestive system neoplasms." (PMID 32756012, 2020). "KLF5, in contrast to KLF4, showed high expression in gastrointestinal tumors." (PMID 34367275, 2021). "Bioinformatics was used for analysis to understand the function and roles of KLF4 and KLF5 in gastrointestinal tumors." (PMID 34367275, 2021). "KLF4 and KLF5 are of great significance for developing gastrointestinal tumors and can be used as therapeutic targets." (PMID 34367275, 2021). "Through bioinformatics analysis, the functions and roles of KLF4 and KLF5 are further elucidated in gastrointestinal tumors." (PMID 34367275, 2021). "KLF4 and KLF5 are members of the KLF transcription factor family, which play an important role in many gastrointestinal tumors." (PMID 34367275, 2021).
hematological malignancies (5 papers, 2015 to 2025). "Disruption of KLF4’s DNA-binding function, as indicated by crystallographic data, may impair macrophage differentiation and has been implicated in hematologic malignancies, such as monocytic leukemia." (PMID 39995670, 2025). "Besides epigenetic regulation, factors such as apoptosis, proliferation control, and microenvironmental influences significantly impact KLF4’s role in hematologic malignancies." (PMID 39995670, 2025). "However, the roles of KLF4 in hematological malignancies and the mechanisms of action are not fully understood." (PMID 25644173, 2015). "Furthermore, KLF4 interacts with other critical factors in hematologic malignancies." (PMID 39995670, 2025).
neurological diseases (4 papers, 2020 to 2024). "Although some evidence has shown that Klf4 plays a critical role in CNS function and susceptibility to some neurological disorders, the specific mechanisms are still obscure." (PMID 39234952, 2024). "In the brain, KLF4 controls various neurophysiological and neuropathological processes, and its contribution to various neurological diseases has been widely reported." (PMID 37996730, 2024).
bacterial infection (3 papers, 2022 to 2025). "Interestingly, while KLF4 deficiency impairs the immune response to bacterial infection, it appears to confer resistance to excessive inflammation in response to direct challenge with endotoxin." (PMID 40831570, 2025). "Our understanding of KLF4 in neutrophils during bacterial infections is primarily based on two studies." (PMID 40313940, 2025). "Overall, KLF4 exerts both pro- and anti-inflammatory effects in bacterial infections, depending on the pathogen, probably cell type (bone marrow derived versus resident macrophages) and immune context." (PMID 40313940, 2025). "For example, we show evidence for a context-specific enhancer linking KLF4 through eQTLs that is only present on bacterial infection in macrophages." (PMID 35751107, 2022). "KLF4 plays a critical role in regulating macrophage responses during bacterial infections." (PMID 40313940, 2025).
head and neck tumors (3 papers, 2018 to 2022). "High expression of KLF4 was associated with good prognosis in BC (HROS = 0.49, 95% CI: 0.33–0.72) and head and neck tumours (HROS = 0.41, 95% CI: 0.23–0.75), which is different from previous results." (PMID 35177016, 2022). "To further assess the clinic correlation of KLF4 and SOX2, we evaluated the expression of KLF4 and SOX2 in the 500 head and neck tumors with RNA sequencing data available from TCGA." (PMID 30108202, 2018).
neurodegenerative disease (3 papers, 2018 to 2024). A disorder of the central nervous system characterized by gradual and progressive loss of neural tissue and neurologic function. "A review of the literature on this area found that KLF4 is associated with neurodegenerative diseases, including PD." (PMID 37996730, 2024). "In neurodegenerative diseases, KLF4 has been found to regulate neuroinflammation, neuronal apoptosis, axon regeneration, and iron accumulation, all of which are relevant to the pathogenesis of AD." (PMID 37996730, 2024). "Given the multifunctionality of KLF4 within CNS, its implication for the management of neurodegenerative disease can be considered." (PMID 37996730, 2024). "Among these transcription factors, the CCAAT enhancer-binding protein beta (CEBPB) and krupple like factor 4 (KLF4) have been documented previously in neurodegenerative diseases." (PMID 34720873, 2021).
digestive system cancer (2 papers, 2017 to 2022). A primary or metastatic malignant neoplasm involving any part of the digestive system. "This study aimed for a comprehensive investigation of the internal associations between KLF4 expression loss and prognostic implications in patients with digestive system cancers." (PMID 29062163, 2017). "In this study, the goal is to determine the prognostic value of loss of KLF4 expression among digestive system cancers via gathering global relevant literatures to perform a systematic analysis." (PMID 29062163, 2017). "The prognostic value of loss of Krüppel-like factor 4 (KLF4) expression in digestive system cancers has not reached a consensus." (PMID 29062163, 2017). "Hence, the prognostic role of KLF4 in patients with digestive system cancers remains disputed." (PMID 29062163, 2017).
heart diseases (1 paper, 2016). "The fourth TF found for the SB gene-TF network (KLF4) is related to vascular and cardiac disease." (PMID 26830357, 2016).
infectious disease (1 paper, 2025). A disorder directly resulting from the presence and activity of a microbial, viral, or parasitic agent in humans. "KLF4 plays a context-dependent role in infectious diseases, exhibiting both pro- and anti-inflammatory effects, depending on a multitude of factors such as context-dependent binding partners, the pathogen, and the cell type in which it is expressed." (PMID 40313940, 2025). "This review aims to summarize current knowledge on the multifaceted roles of KLF4 in phagocytes during infectious diseases." (PMID 40313940, 2025). "Furthermore, future perspectives, such as the therapeutic potential of targeting KLF4 to modulate phagocyte-mediated responses in the treatment of infectious diseases, are discussed." (PMID 40313940, 2025).
KLF4 also shares sentences with these, for which no sentence is quoted: chronic myeloid leukemia (6 papers); skin squamous cell carcinoma (6); brain tumor (5); osteoarthritis (5); abdominal aortic aneurysm (4); Glucose intolerance (4); benign tumors (3); COVID-19 (3); Marfan syndrome (3); type 2 diabetes (3); Cirrhosis (2); Clear Cell Meningioma (2); congenital heart disease (2); cystic fibrosis (2); essential hypertension (2); hematological cancers (2); hyperlipidemia (2); hypertrophy (2); intraventricular meningioma (2); kidney failure (2); laryngeal squamous cell carcinoma (2); lymph node metastasis (2); metabolic disorders (2); Multiple Myeloma (2); multiple sclerosis (2); neuroendocrine lung tumors (2); non-alcoholic fatty liver disease (2); Psammomatous Meningioma (2); rectal cancer (2); small cell lung carcinoma (2).
A further 109 diseases each share a sentence with KLF4 in 2 papers or fewer.